ENSG00000251942
Synonyms: LOC124900528
Gene: Small Cajal body-specific RNA gene on chromosome 2 (53,470,447 to 53,470,629, reverse strand). Ensembl gene ENSG00000251942.
Gene Ontology:
Biological process: RNA processing
Cellular component: nucleolus